ALDH2 (aldehyde dehydrogenase 2 family member)
Diseases named in the same sentence as ALDH2 in open-access papers (continued):
Sharing a sentence is not in itself a finding about the gene and the disease.
Sepsis (10 papers, 2021 to 2026). Sepsis is defined as life-threatening organ dysfunction caused by a dysregulated host response to infection. "In contrast, loss of ALDH2 function significantly aggravates necrotic cell death and cytotoxic activity in endothelial cells during sepsis, whereas treatment with Alda-1 can mitigate these effects." (PMID 40968356, 2025). "Considering that ALDH2 is an essential enzyme of respiratory chain in mitochondria, studies have demonstrated that ALDH2 deficiency generally induces ROS generation, whereas ALDH2 activation alleviates ROS accumulation in various diseases (including sepsis)." (PMID 37064008, 2023). "In this study, we evaluated the effect of aldehyde dehydrogenase (ALDH2) on myocardial pyroptosis and revealed the underlying mechanisms in sepsis." (PMID 36992838, 2023). "This study investigated the possible mechanisms underlying the roles of ALDH2, pyroptosis, and ferroptosis in sepsis-induced lung injury." (PMID 35188436, 2022). "Therefore, we established a murine LPS-induced sepsis model to investigate the potential role and underlying mechanisms of ALDH2 in the pathogenesis of septic AKI." (PMID 37064008, 2023). "In the present study, we found that ALDH2 activation or overexpression could counteract sepsis-associated cardiac injury in vivo by downregulating mitophagy via the mitigation of 4HNE accumulation and MDA formation." (PMID 34025411, 2021). "Third, it has been reported that ALDH2 plays a protective role in sepsis-induced lung injury by inhibiting pyroptosis and ferroptosis." (PMID 40968356, 2025). "Another NETosis marker, aldehyde dehydrogenase 2 (ALDH2), was demonstrated to predict sepsis-related ARDS and mortality in mice." (PMID 40731775, 2025). "In sepsis, mitochondrial aldehyde dehydrogenase 2 (ALDH2) promotes the activation of NLRP3 inflammasome and participates in the occurrence of pyroptosis." (PMID 38698431, 2024). "Compared with the control group, LPS treatment induced a very high murine sepsis score, while Aldh2 knockout (Aldh2−/− genotype) and Alda-1 treatment further aggravated and reduced the score relative to the LPS group, respectively." (PMID 36992838, 2023). "A preliminary study reported that the inhibition of ALDH2 expression in the kidneys aggravated renal injury and inflammation in a sepsis model." (PMID 37064008, 2023). "Previous studies have illustrated that ALDH2 protects against sepsis-induced multiorgan abnormalities." (PMID 37064008, 2023). "The present study demonstrated for the first time the protective effect of ALDH2 on myocardial pyroptosis induced by sepsis." (PMID 36992838, 2023). "The level of plasma LDH, a marker of organ damage, also indicated the protective effect of ALDH2 in sepsis." (PMID 36992838, 2023). "Compared with the control group, 4-HNE significantly increased mtDNA and ox-mtDNA release, while ALDH2 reduced it, suggesting that sepsis triggered mtDNA and ox-mtDNA release through oxidative stress." (PMID 36992838, 2023). "Previous evidence has illustrated an indispensable role of mitochondrial aldehyde dehydrogenase 2 (ALDH2) in the pathogenesis of sepsis-induced multiorgan abnormalities." (PMID 37064008, 2023). "Mitochondrial aldehyde dehydrogenase 2 (ALDH2), an enzyme involved in aldehyde metabolism, exerts a protective effect against sepsis." (PMID 35188436, 2022). "The expression of NLRP3, Caspase-1, GSDMD, IL-1β, and IL-18 was decreased, suggesting that ALDH2 also inhibited pyroptosis in sepsis-induced lung injury." (PMID 35188436, 2022). "The present study explored changes in pyroptosis and ferroptosis in sepsis-induced ALI and analyzed the effect of ALDH2 and its underlying mechanism of action." (PMID 35188436, 2022). "One study demonstrated excessive endoplasmic reticulum stress and mitophagy levels in an animal model of sepsis, which were significantly alleviated in ALDH2 transgenic mice." (PMID 34025411, 2021).
Sepsis (continued). "A previous study revealed likely roles for ALDH2 in the inflammatory response, immunity, and organ dysfunction in sepsis." (PMID 34025411, 2021). "The activation of ALDH2 may alleviate sepsis-induced cardiac dysfunction or acute lung injury severity by modulating endoplasmic reticulum stress, autophagy, and inflammation." (PMID 37064008, 2023). "Moreover, recent studies have shed light on the protective role of ALDH2 in sepsis-induced organ dysfunction." (PMID 37064008, 2023). "Specifically, this study investigated the potential role of ALDH2 in sepsis-induced AKI." (PMID 37064008, 2023). "In this study, we found that ALDH2 remarkably inhibited the cytoplasmic shuttle of HDAC3 induced by sepsis, and it might be related to the binding of the two proteins." (PMID 36992838, 2023). "This study is the first to demonstrate that ALDH2 may inhibit sepsis-induced translocation of HDAC3 from nucleus to mitochondria." (PMID 36992838, 2023). "In this study, we observed a decrease in lung ALDH2 protein expression in mice with sepsis, suggesting that mitochondrial ALDH2 may be an important cause of lung injury in mice with sepsis." (PMID 35188436, 2022). "This study demonstrated that a PTM, phosphorylation of ALDH2, may play a role in the pathogenesis of sepsis and provide a new target for the therapy." (PMID 34745104, 2021). "The present study investigated whether aldehyde dehydrogenase 2 (ALDH2) regulates mitophagy in sepsis-induced myocardial dysfunction." (PMID 34025411, 2021). "ALDH2 protects against heat shock and is involved in the pathogenesis of sepsis." (PMID 34764958, 2021). "In addition, ALDH2 activity was reduced during sepsis, especially in the late phase of sepsis, as shown by an enzyme activity assay." (PMID 34745104, 2021). "During the development of sepsis, increased hepatocyte apoptosis and GSDME-mediated pyroptosis were confirmed to be the major causes of septic liver injury, which could be alleviated by promoting ALDH2 activity." (PMID 40968356, 2025). "Therefore, in the present study, we hypothesized that ALDH2 plays an essential role in sepsis-induced AKI via the inhibition of inflammation, oxidative stress, and apoptosis." (PMID 37064008, 2023). "However, only a few studies have assessed whether ALDH2 can play a protective role against sepsis-induced lung injury by inhibiting pyroptosis and ferroptosis." (PMID 35188436, 2022). "Therefore, we hypothesized that increased ALDH2 activity may have a protective effect on sepsis-induced cardiomyopathy." (PMID 34025411, 2021). "It was found that although HADHA protein levels were unchanged, sepsis significantly reduced HADHA acetylation levels compared with controls, which was reversed by ALDH2." (PMID 36992838, 2023). "During sepsis, MP1 and MP2 are downregulated, whereas MP3 is upregulated concomitantly (MP1 and MP2 shift to MP3), leading to a decrease in the ALDH2 activity." (PMID 34745104, 2021). "As ALDH2 protects cells from acetaldehyde and fatty acid-derived aldehydes (such as 4-HNE), we hypothesized that ALDH2 activation is an effective treatment for sepsis-induced lung injury." (PMID 35188436, 2022). "Our previous studies have demonstrated that activation of ALDH2 could reduce the release of 4-HNE, inhibit oxidative stress, alleviate cardiac and lung injury in diabetic rats, and alleviated kidney injury in rats with sepsis." (PMID 35188436, 2022).
alcoholic cirrhosis (9 papers, 2009 to 2026). "Numerous studies suggest that variations of ALDH2 are associated with the risk for a series of diseases such as alcoholic cirrhosis, cancer, Alzheimer’s and stroke." (PMID 32160861, 2020). "A meta-analysis of 12 studies found that individuals with ALDH2*1 allele are connected with a higher frequency of alcoholic liver cirrhosis (ALC) compared with those with ALDH2*1/*2 or ALDH2*2/*2 genotype 49." (PMID 32140062, 2020). "A common ALDH2 genetic variant among East Asians, including Koreans, affects acetaldehyde levels in the blood and alcohol-associated behavior, increasing the risk for alcoholic cirrhosis." (PMID 39456347, 2024). "Importantly, recent studies indicate that carriers of ALDH2*2 mutation have an increased risk for alcoholic cirrhosis, cancer and CAD." (PMID 32160861, 2020). "Mitochondrial aldehyde dehydrogenase 2 (ALDH2) is critical in the pathogenesis of alcoholic liver cirrhosis." (PMID 29799157, 2018). "Furthermore, it was also recently reported that the combined genotypes of ADH1B rs1229984, ADH1C rs698, and ALDH2 rs671 that do not lead to acetaldehyde accumulation are associated with an increased risk of alcoholic cirrhosis." (PMID 40833357, 2026).
liver fibrosis (9 papers, 2016 to 2025). "ALDH2 deficiency accentuated CCl4-induced hepatic fibrosis via ROS overproduction, while ALDH2−/− mice were prone to get liver inflammation and fibrosis through malondialdehyde-acetaldehyde induced paracrine IL-6 activation in Kupffer cells." (PMID 35864505, 2022). "ALDH2 deficiency accentuated CCl4‐induced liver fibrosis in mice, accompanied by increased expression of collagen 1α1, α‐SMA and TIMP‐1." (PMID 29799157, 2018). "The salient findings of this study revealed that global ALDH2 deficiency aggravated liver injury and liver fibrosis induced by chronic CCl4 exposure, along with ROS overproduction, exacerbated hepatocyte apoptosis and inhibited mitophagy." (PMID 29799157, 2018). "Taken together, our data demonstrated that ALDH2 deficiency may cause deteriorated hepatic fibrosis with markedly increased collagen deposition and profibrotic mRNA expression." (PMID 29799157, 2018). "In summary, our findings demonstrated that ALDH2 plays a vital role in CCl4‐induced mouse liver fibrosis model." (PMID 29799157, 2018). "Then, we used WT and ALDH2−/− mice to further detect the role of ALDH2 in CCl4‐induced liver fibrosis." (PMID 29799157, 2018). "Furthermore, Alda‐1, a specific ALDH2 activator, was administered to further demonstrate the therapeutic effect of ALDH2 activation on liver fibrosis." (PMID 29799157, 2018). "This study aimed to demonstrate whether ALDH2 regulates carbon tetrachloride (CCl4)‐induced liver fibrosis and to investigate the efficacy of Alda‐1, a specific activator of ALDH2, on attenuating liver fibrosis." (PMID 29799157, 2018). "Besides, lentiviral vectors were employed to deliver ALDH2 or inhibit the expression of ALDH2 to further examine the effect of ALDH2 on hepatic fibrosis in vitro." (PMID 29799157, 2018). "Previous results suggested that ALDH2 activation might ameliorate liver fibrosis via alleviating ROS generation." (PMID 29799157, 2018). "The protective role of ALDH2 prompted us to determine whether ALDH2 activation could ameliorate CCl4‐induced liver fibrosis in vivo." (PMID 29799157, 2018). "Furthermore, it also suggested that the alteration of ALDH1B1, ALDH2 and ALDH7A1 levels may be potential biomarkers for the curative effect evaluation of gypenoside against liver fibrosis." (PMID 28291813, 2017). "Notably, future studies should also assess animal body weight, liver fibrosis scores, and standard blood markers of MASLD in our current mouse models, as well as determine whether ALDH2 inhibition or genetic ablation in hepatocyte‐specific cGas knockout mice can reverse HFD‐induced MASLD." (PMID 41042077, 2025).
Myocardial fibrosis (9 papers, 2016 to 2026). "When ALDH2 knockout mice are exposed to alcohol for 6 weeks, higher levels of ROS within the ALDH2 knockout mice with respect to wild type ALDH2 mice were associated with reduced left ventricular ejection fraction and increased myocardial fibrosis." (PMID 39075523, 2024). "Using Aldh2 BM chimeric mice to model AMI, we observed that WT mice transplanted with Aldh2 rs671 donor BM developed severe myocardial fibrosis and markedly reduced cardiac systolic function 2 weeks after infarction compared with controls." (PMID 41734032, 2026). "Diabetic ALDH2*2 mice showed higher aldehyde accumulation, leading to mitochondrial dysfunction, apoptosis, and myocardial fibrosis." (PMID 40564981, 2025). "The upregulation of ALDH2 can inhibit myocardial cell damage induced by high glucose and alleviate myocardial fibrosis in rats." (PMID 38609879, 2024). "Activation of ALDH2 can reduce myocardial fibrosis in diabetic rats and inhibit the expression of JNK (c-Jun N-terminal kinase) which is important in cell proliferation, differentiation, apoptosis, fibrosis, and so on." (PMID 29129988, 2017). "In the light of our own and others' research, we speculate that ALDH2 may be expressed in cardiac fibroblasts and is involved in the occurrence of myocardial fibrosis." (PMID 29129988, 2017). "With low dose ethanol intervention, enhanced ALDH2 expression can antagonize the happening of myocardial fibrosis in diabetic rats, which may be relevant with downregulating the JNK pathway." (PMID 27547765, 2016). "Similarly, another potent ALDH2 activator, AD-9308, significantly improves diastolic and systolic myocardial function in diabetic models by enhancing mitochondrial respiration and reducing myocardial fibrosis, highlighting its potential to mitigate cardiac remodeling in DCM." (PMID 40564981, 2025). "After treated with daidzin, the ALDH2-specific antagonist, ALDH2 activity and expression were decreased; the synthesis of collagen I and collagen III were increased, aggravating myocardial fibrosis, and further verified the key role of ALDH2." (PMID 29129988, 2017). "We have verified that when treated with a low concentration of ethanol, the nonselective agonist of ALDH2, myocardial fibrosis was improved in diabetic rat." (PMID 29129988, 2017). "When CFs were treated with high glucose and ALDH2 agonist Alda-1, ALDH2 activity and expression were increased while the collagen I and collagen III mRNA expressions were decreased, it suggested that Alda-1 promote the expression of ALDH2, and the increase of ALDH2 can reverse myocardial fibrosis." (PMID 29129988, 2017).
atrial fibrillation (8 papers, 2016 to 2026). A disorder characterized by an electrocardiographic finding of a supraventricular arrhythmia characterized by the replacement of consistent P waves by rapid oscillations or fibrillatory waves that vary in size, shape and timing and are accompanied by an irregular ventricular response. "The polymorphism of ALDH2 gene is a high risk factor for CAD in patients with atrial fibrillation." (PMID 41551908, 2026). "Likewise, our recent work also showed ALDH2 variants are prone to the development of atrial fibrillation and impaired atrial function with light-to-moderate alcohol use48." (PMID 37280327, 2023). "Lots of gene variants have been associated with atrial fibrillation (AF), among which the association between ALDH2 rs671 polymorphism and AF is variable." (PMID 36426220, 2022). "Alcohol—a risk factor for atrial fibrillation (AF)—is metabolized by aldehyde dehydrogenase 2 (ALDH2)." (PMID 36340257, 2022). "In patients with atrial fibrillation, the risk of CAD in patients with ALDH2 mutant genotype (GA + AA) was 5.849 times that of ALDH2 wild‐type genotype (GG) (95%CI = 1.437–23.795, p < 0.05)." (PMID 41551908, 2026). "The extent to which low alcohol consumption may cause atrial substrates to trigger atrial fibrillation (AF) development in users with ALDH2 variants remains to be determined." (PMID 34827557, 2021). "A study conducted in ALDH2*2 mutant mice demonstrated that coenzyme Q10—in addition to improving mitochondrial oxidative stress and preserving bioenergetics—is effective in protecting against attacks of atrial fibrillation (AF)." (PMID 36555095, 2022).
head and neck squamous cell carcinoma (8 papers, 2016 to 2026). A squamous cell carcinoma that arises from any of the following anatomic sites: lip and oral cavity, nasal cavity, paranasal sinuses, pharynx, larynx, and salivary glands. "In head and neck squamous cell carcinoma, ALDH2 is associated with CD8+ T cell infiltration in the tumor microenvironment." (PMID 38378847, 2024). "Genetic polymorphisms in ADH1B and/or ALDH2 can result in different enzymatic activities that have a major impact on the risk of ESCC as well as head and neck squamous cell carcinoma (HNSCC)." (PMID 28891965, 2017). "In this study, heavy alcohol drinking downregulated ALDH2 gene expression while heavy smoking up-regulated SOD2 gene expression in head and neck squamous cell carcinoma patients (N = 270)." (PMID 28841898, 2017). "An increase of cisplatin-induced DNA damage was reported in head and neck squamous cell carcinoma (HNSCC) cells with reduced ALDH2 activity." (PMID 28532411, 2017). "The association between alcohol drinking, aldehyde dehydrogenase 2 (ALDH2) polymorphism, and survival in patients with head and neck squamous cell carcinoma (HNSCC) remains unclear." (PMID 26804037, 2016). "Additionally, diminished ALDH2 expression is associated with lower survival rates in skin cutaneous melanoma (SKCM), head and neck squamous cell carcinoma (HNSC), kidney chromophobe (KICH), KIRC, KIRP, brain low-grade glioma (LGG), LIHC, and mesothelioma (MESO)." (PMID 38911385, 2024).
prostate carcinoma (8 papers, 2015 to 2024). A carcinoma that arises from epithelial cells of the prostate gland. "A further ALDH isoform, ALDH2, has previously been associated with the progression of benign prostatic hyperplasia, but this study represents the first to specifically link it with lethal prostate cancer." (PMID 27980733, 2016). "Although prostate cancer has high ALDH2 expression with high OS, its ALDH1A1 expression is indeed very low." (PMID 29552329, 2018). "Piperlongumine was suggested to increase the activity of recombinant ALDH2 and protect it from inactivation by lipid aldehydes; thus, we speculated that this drug could play a role in the treatment of prostate cancer in the future." (PMID 36144737, 2022).
alcohol intolerance (7 papers, 2011 to 2025). "A key factor influencing alcohol use among Asians is alcohol intolerance, caused by the ALDH2*2 (rs671), ADH1B*2 (rs1229984), and other alleles for alcohol metabolism." (PMID 41302551, 2025). "Conversely, the rs671 variant in ALDH2 appeared to have a protective effect, potentially mediated by reduced alcohol consumption, among carriers with alcohol intolerance." (PMID 40699860, 2025). "In contrast to the known functional consequence of the ALDH2*2 variant (rs671) in East Asians, which is associated with alcohol intolerance, in Europeans the beneficial derived alleles are associated with increased ALDH2 gene expression." (PMID 35296751, 2022). "An ALDH2 allele, rs671 A, is an allele responsible for alcohol intolerance, which causes marked facial flushing and mild to moderate symptoms of intoxication." (PMID 33004991, 2020). "One limitation is that our sample included Asian students from diverse backgrounds rather than being limited to East Asian ancestry, which is more strongly associated with genetic variants linked to alcohol intolerance and flushing [e.g., ALDH2*2 (rs671) and ADH1B*2 (rs1229984)]." (PMID 41302551, 2025). "Nevertheless, since quercetin enhanced acetaldehyde tolerance via the HO-1-dependent antioxidant mechanism, quercetin may improve the symptoms caused by ALDH2 polymorphism-dependent alcohol intolerance." (PMID 39201725, 2024). "Since the supportive ALDH isozymes rather than ALDH2 might contribute to the cytoprotective effect of quercetin against acetaldehyde, quercetin is anticipated to prevent the adverse reactions associated with the alcohol intolerance caused by ALDH2 polymorphism, characteristic of East Asians." (PMID 39201725, 2024). "Both rs671 (G > A) in ALDH2 and rs1229984 (T > C) in ADH1B were examined as markers of alcohol intolerance." (PMID 38328521, 2023).